TMF1 (TATA element modulatory factor 1)
Description:
Potential coactivator of the androgen receptor. Mediates STAT3 degradation. May play critical roles in two RAB6-dependent retrograde transport processes: one from endosomes to the Golgi and the other from the Golgi to the ER. This protein binds the HIV-1 TATA element and inhibits transcriptional activation by the TATA-binding protein (TBP).
Synonyms: TMF; ARA160
Tractability: PROTAC: ubiquitination databases record sites on it; its protein half-life has been measured.
Gene: Protein-coding gene on chromosome 3 (69,019,827 to 69,052,339, reverse strand). Ensembl gene ENSG00000144747.
Subcellular location: Cytoplasm; Nucleus; Golgi apparatus membrane
Subcellular location (Human Protein Atlas): Golgi apparatus
Pathways (Reactome):
Vesicle-mediated transport: Retrograde transport at the Trans-Golgi-Network
Gene Ontology:
Molecular function: nuclear androgen receptor binding; protein binding; transcription coactivator activity
Biological process: androgen receptor signaling pathway; positive regulation of transcription by RNA polymerase II; retrograde transport, endosome to Golgi; retrograde vesicle-mediated transport, Golgi to endoplasmic reticulum; regulation of proteasomal protein catabolic process
Cellular component: Golgi apparatus; cytosol; endoplasmic reticulum; cytoplasm; Golgi membrane; nucleus
Genetic constraint (gnomAD): Loss-of-function variants: 54 observed, 109.32 expected, observed/expected ratio (o/e) 0.49, 90% interval 0.4 to 0.62. The upper end of that interval is the gene's LOEUF score, 0.62, which puts it in group 2 of 6, group 1 being the genes least tolerant of losing a copy. Missense variants: 1,126 observed, 1,177.7 expected, observed/expected ratio (o/e) 0.96, 90% interval 0.91 to 1. Synonymous variants: 417 observed, 410.47 expected, observed/expected ratio (o/e) 1.02, 90% interval 0.94 to 1.1.
Homologues: Orthologues: chimpanzee TMF1 (99% identical), macaque TMF1 (96% identical), pig TMF1 (93% identical), dog TMF1 (93% identical), rabbit TMF1 (92% identical), guinea pig TMF1 (91% identical), mouse Tmf1 (87% identical), rat Tmf1 (85% identical), tropical clawed frog tmf1 (63% identical), zebrafish tmf1 (60% identical). Paralogues in human: MYO18A (22% identical), MYO18B (20% identical), MYH3 (15% identical), MYH2 (14% identical), MYH8 (14% identical), MYH1 (14% identical), MYH11 (14% identical), MYH4 (14% identical), MYH6 (14% identical), MYH7 (14% identical), MYH7B (14% identical), MYH10 (14% identical), and 32 more.
Diseases named in the same sentence as TMF1 in open-access papers:
TMF1 is named in the same sentence as 12 diseases in open-access papers, as found by Europe PMC text mining. Sharing a sentence is not in itself a finding about the gene and the disease. The quoted sentences say what the papers report.
colon cancer (1 paper, 2023). "One might suggest that the TMF1 gene expression may have a role in tumorigenesis in colon cancer due to its high correlation with the BCLAF1 gene expression." (PMID 36109686, 2023).
Hyperglycemia (1 paper, 2023). An increased concentration of glucose in the blood. "In that study, the absence of TMF1 led to the retention of GLUT4 in perinuclear compartments and hyperglycemia was induced in TMF1 knockout mice." (PMID 37762604, 2023).
male infertility (1 paper, 2025). The inability of the male to effect fertilization of an ovum after a specified period of unprotected intercourse. "The first pathogenic variant in the TATA element modulatory factor 1 (TMF1: c.2859+4A>G) results in TMF1 exon 14 skipping and decreased progressive sperm motility and morphological abnormalities in a patient with male infertility." (PMID 41168986, 2025).
soft tissue sarcoma (1 paper, 2020). A malignant neoplasm arising from muscle tissue, adipose tissue, blood vessels, fibrous tissue, or other supportive tissues excluding the bones. "In a previous study, RAF1 fusions were reported in soft tissue sarcoma, in which the fusion counterparts, PDZRN3, SLMAP and TMF1, were identified in three of eight cases." (PMID 32825119, 2020).
tumor (2 papers, 2019 to 2022). "In our data, the expression of epithelial cilium movement markers, including FOXJ1, PRG, RFX2, and TMF1, although increased during the process, were mainly overexpressed in primary tumor cells." (PMID 35935940, 2022).
TMF1 also shares sentences with these, for which no sentence is quoted: cancer (3 papers); anaplastic meningioma (1); benign meningioma (1); Chronic colitis (1); chronic granulomatous disease (1); prostate tumor (1); pulmonary arterial hypertension (1).